PLS3 (plastin 3)
Diseases named in the same sentence as PLS3 in open-access papers (continued):
Sharing a sentence is not in itself a finding about the gene and the disease.
cancer (22 papers, 2006 to 2025). A tumor composed of atypical neoplastic, often pleomorphic cells that invade other tissues. "Aberrantly decreased or increased PLS3 level was reported to be linked with the development and/or severity of cancer, bone disorders and neurodegeneration disorders." (PMID 35752817, 2022). "Chromosomal instability, a hallmark of cancer formation, can trigger a copy number gain of Xq23 leading to PLS3 overexpression." (PMID 34023917, 2021). "PLS3 encodes a protein called plastin-3 that is found in cancer cells." (PMID 37397367, 2023). "The aberrant expression of PLS3 was reported in a wide range of cancers, and its expression is closely associated with the EMT-induced malignant phenotypes of cancers." (PMID 35409173, 2022). "Through the PI3K/AKT signaling pathway, PLS3 regulates tumor progression by promoting the proliferation and migration of cancer cells." (PMID 34023917, 2021). "In a recent study, a peptide library has been screened for affinity to PLS3-overexpressing cancer cells." (PMID 34023917, 2021). "PLS3 overexpression is strongly correlated with several cancer types, and has been recommended for use as biomarker in cancer and poor prognosis for survival." (PMID 34023917, 2021). "Elevated PLS3 levels are considered a prognostic biomarker for cancer and refractory response to therapies." (PMID 34023917, 2021). "A recent study has also found that promoter-specific hypomethylation induces the ectopic expression of the cancer-related genes PLS3, GATA6 and TWIST1 in SS." (PMID 30701021, 2018). "When we reduced PLS3 in cancer cells, they grew more slowly, moved less, and were less invasive." (PMID 41375083, 2025). "We discovered that PLS3 works by helping cancer cells become more mobile and invasive." (PMID 41375083, 2025). "This could enable the measurement of expressions of certain molecular markers, such as the epithelial marker cytokeratin 19, mesenchymal marker plastin 3, and cancer stem markers ALDH1, CD133, and CD44." (PMID 36835361, 2023). "Three plastin isoforms are expressed in vertebrates: PLS1 (I-plastin) is expressed in absorptive intestinal and kidney cells, PLS2 (LCP, LCP1, or L-plastin) is predominantly found in hematopoietic and cancer cells, while PLS3 (T-plastin) is ubiquitously expressed in all solid tissues." (PMID 37484945, 2023). "When escaping X-inactivation, PLS3 triggers a plethora of different types of cancers." (PMID 34023917, 2021). "The involvement of PLS3 in cancer biology was described in a number of studies." (PMID 31717802, 2019). "In human cancer cell lines high PLS3 expression correlates with mesenchymal, stemness and metastatic gene expression signature, which suggests that PLS3 may also be treated as a marker of aggressiveness and metastatic potential." (PMID 30634453, 2019). "Moreover, PLS3 expression was discovered as potential marker for circulating tumor cells undergoing epithelial-mesenchymal transition in a variety of cancers." (PMID 31717802, 2019). "Interestingly, PLST belongs to the plastin protein family of three isoforms with relatively high homology between: I (plastin-1 expressed in the intestine and kidney), L (plastin-2 in leukocytes and cancer) and T (plastin-3 in solid tissues)." (PMID 25525413, 2014). "Finally, pls3 was found by differential display to have increased expression in cisplatin-resistant human cancer cells." (PMID 16420690, 2006). "Altered PLS3 expression was reported to be associated with human carcinogenesis, including PDA, and the detection of PLS3 expression may predict prognosis in various human cancers." (PMID 34348730, 2021). "Here, PLS3 acts as an oncogene and its overexpression triggers the activation of the PI3K/AKT signaling pathway leading to cancer progression." (PMID 34023917, 2021).
cancer (continued). "PLS1 (plastin 1, I-plastin) is expressed in the intestine, colon, kidney and hair cell stereocilia of the inner ear, PLS2 (plastin 2, L-plastin) in hematopoietic cell lineages and many types of cancer cells, and PLS3 (plastin 3, T-plastin), the most abundant isoform, in cells from solid tissues." (PMID 34023917, 2021). "Within the favorable genes, UNC13B, and SFXN2 cover nine cancer types and in the same way, SLC2A1, PLS3, SLC16A1, and SLC16A3 within the unfavorable set of genes and could serve as novel target structures." (PMID 32599841, 2020). "A direct function of PLS3 as transport protein is not known in the analyzed cancer entities." (PMID 32599841, 2020).
tumor (21 papers, 2009 to 2025). "Regarding PLS3, one recent study that included 207 PDA tissue specimens showed that the overexpression of PLS3 was associated with tumor stage and pathology as well as poor OS in PDA patients." (PMID 34348730, 2021). "Notably, single-cell transcriptomic profiling of T follicular helper cell lymphomas identified PLS3 as a tumor-specific marker linked to immune evasion and drug resistance." (PMID 41375083, 2025). "In another study, PLS3 expression on circulating tumor cells could be linked to lymph node metastasis." (PMID 31717802, 2019). "Additionally, high PLS3 levels were linked to a weaker immune response against the tumor." (PMID 41375083, 2025). "Functional assays in vitro and in vivo illustrated that PLS3 knockdown suppressed tumor growth, migration, and metastatic processes." (PMID 41375083, 2025). "Given the key role of chemokine networks in regulating immune cell trafficking and tumor immune evasion, this study systematically delineated the relationship of PLS3 expression with immune phenotypes within the TME." (PMID 41375083, 2025). "Despite its established role in tumor progression, PLS3’s contribution to immune microenvironment regulation remains largely unexplored." (PMID 41375083, 2025). "Our findings suggest that PLS3 not only promotes tumor progression through EMT but also facilitates T cell anti-tumor immunity by modulating the tumor microenvironment." (PMID 41375083, 2025). "Knockdown of PLS3 inhibited cell proliferation, migration, and invasion in vitro, and suppressed tumor growth in vivo." (PMID 41375083, 2025). "Plastin-3 (PLS3), an actin-bundling protein critical for cytoskeletal remodeling, has been implicated in tumor metastatic cascades through its regulation of mechanosensory signaling." (PMID 41375083, 2025). "Considering the critical function of EMT in tumor invasion and metastasis, we established stable PLS3-knockdown HSC3 and SCC25 cell models via lentiviral shRNA." (PMID 41375083, 2025). "Our findings suggest that PLS3 not only promotes tumor progression through EMT but also facilitates immune evasion by modulating the TME." (PMID 41375083, 2025). "High PLS3 expression was strongly related with adverse clinical outcomes, encompassing advanced tumor stage as well as poor overall survival." (PMID 41375083, 2025). "We identified PLS3 as a tumor-specific marker through scRNA-seq and further confirmed its protein expression on the PTCL tumor cell-surface." (PMID 38012392, 2024). "Unexpectedly, PLS3 and vimentin expression levels were lower in tumor tissues than in normal tissues (p < 0.001)." (PMID 31947504, 2020). "In 52 patients, discordance between primary tumor and CTCs was 5.77% for KRAS, 3.85% for BRAF, 11.54% for CD133 rs3130, 7.69% for CD133 rs2286455 and 11.54% for PLS3 rs6643869 mutations." (PMID 25902072, 2015). "Notably, in HNSCC, PLS3 mRNA levels were notably higher in tumor tissues relative to adjacent normal controls." (PMID 41375083, 2025). "Furthermore, immunohistochemical (IHC) staining of 30 primary HNSCC tumor samples and 21 adjacent normal tissues demonstrated markedly elevated PLS3 protein expression in tumors." (PMID 41375083, 2025). "Our study analyzed significant upregulation of PLS3 in HNSCC tumor tissues compared to normal ones." (PMID 41375083, 2025). "The actin‐binding protein PLS3 (Plastin‐3) is involved in tumor metastasis, yet its expression, function, and therapeutic potential in HNSCC remain unclear." (PMID 41375083, 2025). "In addition, high expression of PLS3 was also related to tumor progression, in several types of tumors." (PMID 35625426, 2022). "Collectively, these results suggested that the tumor-suppressive effects of ZNF471 on cell proliferation, migration, and invasion are associated with the transcriptional suppression of its downstream target TFAP2A and PLS3." (PMID 29610526, 2018).
tumor (continued). "In fact, we found several proteins possibly involved in actin cytoskeleton organization and cell-cell junction assembly, including talin-1, ezrin, plastin-3, fascin, catenin alpha-1, filamins A and B to be up-regulated in tumor tissues compared to control tissues." (PMID 24858105, 2014). "Additionally, we identified a novel tumor-cell-specific marker, PLS3." (PMID 38012392, 2024). "While for SLC2A1 this could be explained by the functional support of the tumor cells with glucose, there is no explanation if PLS3 is functionally associated with tumor progression." (PMID 32599841, 2020). "PLS3 was knocked down in vitro to assess its effects on HNSCC cell functions, and in vivo models were established to evaluate tumor progression and immune microenvironment." (PMID 41375083, 2025). "This dual-axis mechanism provides a comprehensive understanding of how PLS3 drives HNSCC progression and emphasizes its possibility as a treatment target for both anti-tumor and immune-modulatory strategies." (PMID 41375083, 2025). "In HNSCC, PLS3 knockdown attenuates LONP2-driven oncogenicity, further supporting its tumor-promoting function." (PMID 41375083, 2025). "This dual-axis mechanism provides a comprehensive understanding of how PLS3 drives HNSCC progression and demonstrates its value as a therapeutic target for both anti-tumor as well as immune-modulatory strategies." (PMID 41375083, 2025). "The tumor-suppressive function of ZNF471 was mediated by directly inhibiting its downstream targets TFAP2A and PLS3 transcription." (PMID 29610526, 2018). "We therefore combined the expression values for the genes identified above (DDIT3, HOXD10, PDE1C, PLS3, PTEN and TUSC3) into a single value per tumor sample, termed 'GNS signature score'." (PMID 23046790, 2012). "Notably, these findings present the first validation that PLS3 drives invasive traits in HNSCC by triggering EMT, thus unraveling a molecular mechanism behind its tumor-promoting function." (PMID 41375083, 2025). "In our study, we found PLS3 is closely related with the TME, especially with the activation and infiltration of CD8+ T cells, suggesting that targeting PLS3 is likely to boost the anti-tumor activity of CD8+ T cells, thus improving the anti-tumor effectiveness in HNSCC." (PMID 41375083, 2025). "Molecularly, PLS3 regulates the PI3K/AKT signaling pathway and the EMT in tumor cells." (PMID 34348730, 2021).
neurodegenerative disease (5 papers, 2010 to 2023). A disorder of the central nervous system characterized by gradual and progressive loss of neural tissue and neurologic function. "PLS3 overexpression plays a protective role in several neurodegenerative diseases associated with decreased F-actin levels, whereas S-nitrosylation of PLS3 is linked to thoracic aortic dissection." (PMID 37484945, 2023). "With the notion that common mechanisms may underlie neurodegenerative diseases, increased PLS3 expression may modify defects associated with other neurodegenerative diseases besides SMA." (PMID 32938453, 2020). "Importantly, PLS3 has been linked to numerous proteins associated with various neurodegenerative diseases." (PMID 31607845, 2019). "To determine if PLS3 is beneficial outside of neurodegenerative disease models, we examined the impact of overexpression on animals with decreased locomotion due to synaptic defects." (PMID 32938453, 2020).
infection (1 paper, 2021). The state of being infected such as from the introduction of a foreign agent such as serum, vaccine, antigenic substance or organism. "In Rickettsia, PLS3 together with profilin, capping protein, and cofilin determine the actin tail length required for motility during infection." (PMID 34023917, 2021). "These include cell migration and growth, axonal and neurite outgrowth of polarized cells, axonal local translation, endocytosis, influence of intracellular calcium on PLS3-dependent processes, mechanotransduction, signaling, infection with pathogens and others." (PMID 34023917, 2021). "Consequently, PLS3 is involved in all processes dependent on F-actin dynamics such as cell motility, focal adhesion, cell division, endocytosis, neurotransmission, vesicle trafficking, axonal local translation, intracellular calcium PLS3-dependent processes, pathogen infection and others." (PMID 34023917, 2021). "During infection with the Hepatitis C virus (HCV), PLS3 has been shown to regulate pathogen replication." (PMID 34023917, 2021).
skeletal dysplasia (1 paper, 2018). Any Mendelian diseases that affects growth and development of the skeleton. "This included seven genes (LIFR, TMEM38B, PLS3, NANS, SLC26A2, ALX4, and PLS3) associated with skeletal dysplasia or bone disease, and four of them were ARE-containing genes with increased expression." (PMID 29727687, 2018).
PLS3 also shares sentences with these, for which no sentence is quoted: amyotrophic lateral sclerosis (2 papers); bone disorder (2); Childhood onset (2); pancreatic adenocarcinoma (2); acute leukemia (1); angioimmunoblastic T-cell lymphoma (1); Atrophy (1); autosomal recessive polycystic kidney disease (1); B-cell lymphomas (1); collagenopathies (1); developmental delay (1); diabetes (1); diffuse large B-cell lymphoma (1); Ehlers-Danlos syndrome (1); epilepsy (1); glioma (1); hepatocellular carcinoma (1); hypophosphatasia (1); inflammatory skin disease (1); liver cirrhosis (1); lung adenocarcinoma (1); myopia (1); Osteogenesis (1); osteoporosis-pseudoglioma syndrome (1); postmenopausal osteoporosis (1); retinal degeneration (1); schizophrenia (1); SOPH syndrome (1); Stomach (1); T-cell lymphomas (1).
A further 2 diseases each share a sentence with PLS3 in 1 paper.